DINOL (damage induced long noncoding RNA)
Synonyms: DINO
Gene: Long non-coding RNA gene on chromosome 6 (36,677,609 to 36,678,559, reverse strand). Ensembl gene ENSG00000285244.
Diseases named in the same sentence as DINOL in open-access papers:
DINOL is named in the same sentence as 5 diseases in open-access papers, as found by Europe PMC text mining. Sharing a sentence is not in itself a finding about the gene and the disease.
cervical cancer (2 papers, 2020 to 2022). A primary or metastatic malignant neoplasm involving the cervix.
cancer (4 papers, 2022 to 2023). A tumor composed of atypical neoplastic, often pleomorphic cells that invade other tissues.
DINOL also shares sentences with these, for which no sentence is quoted: tumor (3 papers); B cell lymphomas (1); sarcoma (1).